ERAP1 (endoplasmic reticulum aminopeptidase 1)
Diseases named in the same sentence as ERAP1 in open-access papers (continued):
Sharing a sentence is not in itself a finding about the gene and the disease.
psoriasis (continued). "Despite these complications, large effect size interactions between loci have been successfully mapped in polygenic human disease (ankylosing spondylitis: HLA-B27 and ERAP1; psoriasis: ERAP1 and HLA-Cw6)." (PMID 31787039, 2020). "PSORS (psoriasis-susceptibility) loci harbor several genes that are involve in psoriasis; for example, HLA-Cw6, ERAP1, ERAP2, and MICA are involved in antigen presentation." (PMID 32671018, 2020). "ERAP1, IL23R, and different MHC class I associations have also been reported for AS, psoriasis, and uveitis." (PMID 31849945, 2019). "Studies have also shown that both the ZNF816A and GJB2 loci are significantly associated with psoriasis in the German population, while ERAP1 and ZNF816A are associated with type 1 (early-onset) psoriasis in the Chinese Han population." (PMID 29292715, 2017). "The review of SNPs of CSTA, ERAP1 and ZAP70 genes, which were tested for correlation with the risk of psoriasis." (PMID 27658291, 2016). "Genetic variations in ERAP1, IL23R, and LCE3B/LCE3C have recently been associated with pediatric-onset psoriasis (onset < age 18) in a small study." (PMID 24175098, 2013). "Another mechanism through which ERAP1 may interact with HLA-C06:02 in Psoriasis involves the enzymatic trimming of NH2-terminal elongated peptide precursors to the appropriate length, thereby facilitating their presentation by HLA-C06:02." (PMID 38892265, 2024). "ERAP1 has been shown to regulate anti-melanocyte antibody production in psoriasis." (PMID 39337694, 2024). "ERAP1 has been related to psoriasis in Chinese (rs151823) and European (rs27524) populations." (PMID 36425068, 2022). "On the other hand, in AS and psoriasis, an inefficient ERAP1 enzyme could fail to produce a disease-promoting peptide." (PMID 33912164, 2021). "ERAP2 was established upon controlling for the contribution of ERAP1 in psoriasis." (PMID 34395615, 2021). "Indeed, changes in the immunopeptidome due to ERAP1 SNPs are exacerbated in the individuals carrying HLA class I loci conferring risks to disease—HLA-B27 for AS, HLA-Cw*06 for psoriasis, and HLA-B*51 for BD." (PMID 32824160, 2020). "Similarly to AS and BD, further investigation revealed significant evidence for the interaction between ERAP1 and HLA-C loci in psoriasis, with a combined significance of P = 6.95 × 10−6." (PMID 30054427, 2018). "Finally, epistatic interactions between MHC class I and ERAP1 have been described for AS, psoriasis, and Behçet’s disease." (PMID 28449694, 2017). "Our aim was to compare psoriasis genetic risk score (GRS) for five susceptibility loci involved in the immunological response (HLA-C, ERAP1, ZAP70) and in the skin barrier function (LCE3, CSTA) between patients with chronic plaque psoriasis (n = 148) and the control group (n = 146)." (PMID 27658291, 2016). "GWAS have identified 40 loci in patients with psoriasis, many of which are related to immune function, including the endoplasmic reticulum aminopeptidase 1 (ERAP1), whose product is relevant to peptides binding to the MHC class I molecules, especially HLA-C*0602 and HLA-B*2746." (PMID 27928500, 2016). "Insufficient generation of self-peptides in B cells, which can cross-activate an autoimmune response against melanocytes, due to differences in proteasomal antigen processing and ERAP1 haplotypes, could be one reason that only a fraction of HLA-C*06:02 carriers eventually develop psoriasis." (PMID 41440022, 2025). "The association at the ERAP1 locus is a novel finding in the context of PUUV infection yet the gene has previously been linked to various autoimmune disorders such as ankylosing spondylitis and psoriasis, as well as infections including hepatitis C, influenza, and HIV." (PMID 39533856, 2025).
psoriasis (continued). "The main issues addressed in our study were: (i) whether smokers and never-smokers differ in the associations of APM polymorphisms with NSCLC risk and clinical outcome, (ii) whether ERAP2 influences the ERAP1 effect, if any, as we observed it in other diseases—psoriasis, and ankylosing spondylitis." (PMID 34149699, 2021). "In particular, we suggest experimental validation of miRNAs hsa-miR-485-3p and hsa-miR-371a-3p and lncRNAs MAP3K14, ERAP1 and SPEN in skin lesions of psoriasis patients treated with biological drugs." (PMID 39337694, 2024). "Epistasis between ERAP1 and MHC class I was also observed in other MHC-I-opathies, such as AS and psoriasis." (PMID 33912164, 2021). "Also, Erap1 and Erap2, which encode for aminopeptidases involved in processing of peptides for presentation by MHC class I molecules, have been identified as susceptibility genes, with ERAP1 variants interacting with HLA-Cw*0602 and increasing the risk for psoriasis." (PMID 29316631, 2018). "Defining the association of ERAP2 with psoriasis has been complicated due to the seemingly non-epistatic nature of this association, the heterogeneity of the disease and the apparently opposite effects of ERAP1 and ERAP2 in the same haplotype, leading to a masking of the latter by ERAP1." (PMID 30425713, 2018). "Hence, the generation of the psoriatic autoantigen by ERAP1 and its presentation by HLA-C*06:02 on melanocytes are essential events in the induction of the autoimmune response by CD8+ T-cells in psoriasis." (PMID 40243413, 2025). "Taken together, these molecular biological findings suggest that ERAP1 might regulate the expression of IFIH1, but more basic biological studies are needed to determine how this gene interaction affects psoriasis." (PMID 36425068, 2022).
ankylosing spondylitis (46 papers, 2009 to 2026). An autoimmune chronic inflammatory disorder characterized by inflammation in the vertebral joints of the spine and sacroiliac joints. "The initial data indicated that the association between Ankylosing Spondylitis and ERAP1, specifically the rs30187 variant, was limited to cases that tested positive for HLA-B27." (PMID 38892265, 2024). "The association of Ankylosing Spondylitis with aminopeptidases located either inside the endoplasmic reticulum (ER)—such as ERAP1, ERAP2, and LNPEP —or in the cytoplasm—specifically NPEPPS —highlights the importance of this process." (PMID 38892265, 2024). "Epistasis of ERAP1 single nucleotide variations (SNVs) and HLA-B27 has been linked to ankylosing spondylitis susceptibility (AS)." (PMID 35954271, 2022). "As ERAP1 polymorphisms have been linked with inflammatory arthritic disease ankylosing spondylitis, we wished to study the role of ERAP1 in relation to the NLRP3 inflammasome specifically in arthritis-linked disorders." (PMID 35246034, 2022). "ERAP1 polymorphism was first reported to be associated with the disease of ankylosing spondylitis in 2007." (PMID 34395615, 2021). "An ERAP1 coding variant, Arg725Gln, confers risk to BD but is protective for ankylosing spondylitis." (PMID 32161166, 2020). "Similar epistatic interactions between HLA class I and ERAP1 have been reported in HLA-B*27-associated ankylosing spondylitis and HLA-C*0602-associated psoriasis." (PMID 32161166, 2020). "Here we found that the two previously identified ankylosing spondylitis-risk variants were associated, in an additive manner, with increasing levels of circulating ERAP1 protein." (PMID 28240269, 2017). "Human leucocyte antigen (HLA)-B27 and endoplasmic reticulum aminopeptidase 1 (ERAP1) are strongly associated with ankylosing spondylitis (AS)." (PMID 26130142, 2016). "Indeed, in the case of the MHCI-allele–dependent inflammatory disease, Ankylosing Spondylitis, the pathogenetic role of ERAP1 has also been proposed to be linked to ER misfolding of HLA-B∗27, the formation of heavy chain dimers and general ER stress." (PMID 40189142, 2025). "However, the involvement of ERAP1 in the pathogenesis of Ankylosing Spondylitis extends beyond its association with the HLA-B27 molecule." (PMID 38892265, 2024). "Given that we previously published ERAP1 deficient mice have enhanced bony fusions in a phenotype similar to ankylosing spondylitis, and our results demonstrating that ERAP1-deficient BMDMs have elevated IL-1β production, we wished to study the impact of MSU crystals on ERAP−/− cells." (PMID 35246034, 2022). "The restriction of the association of ERAP1 with ankylosing spondylitis to HLA-B27-positive patients is consistent with disease models in which aberrant trimming of peptides or presentation by ERAP1 and HLA-B27 are involved in the pathogenesis of HLA-B27-associated disease." (PMID 35629038, 2022). "Evidence has suggested that ERAP1 variants have an established role in autoimmune disorders, which has been described in ERAP1 deficient mice that exhibit reduced T and dendritic cell count, linked with ankylosing spondylitis." (PMID 36544093, 2022). "Interestingly, Lachnospiraceae was the most differentially regulated microbial family in the terminal ileum of patients with ankylosing spondylitis, a disease associated with polymorphisms in ERAP1." (PMID 29378630, 2018). "Similarly, mRNA sequences isolated from lymphoblastoid cells showed that ERAP1 mRNA expression also increased with increasing numbers of ankylosing spondylitis-risk alleles." (PMID 28240269, 2017). "In addition, the ERAP1 (rs30187) polymorphism which encodes an endoplasmic reticulum aminopeptidase is involved in peptide trimming before HLA class I presentation and only affects ankylosing spondylitis risk in HLA-B27-positive individuals." (PMID 23308121, 2013).
ankylosing spondylitis (continued). "In addition to their association with KD, ERAP1 polymorphisms have been found to be associated with ankylosing spondylitis, an HLA class I–mediated autoimmune disease, and enthesitis, a common inflammatory arthritis characterized by axial skeletal inflammation." (PMID 21326860, 2011). "Among these, the presence of ERAP1 is currently recognized as the second-most-important genetic determinant of Ankylosing Spondylitis after HLA-B27; however, the exact mechanism that confers this increased risk remains uncertain." (PMID 38892265, 2024). "Several groups of researchers examined the role of ERAP1 and ERAP2 as ankylosing spondylitis risk factors in addition to HLA-B*27 (reviewed by 17, 18, 26, 56–58)." (PMID 35769458, 2022). "So far, ERAP-1 was mostly known for the link between ERAP-1 allotypes and HLA-associated autoinflammatory diseases, such as the HLA-B*27-associated ankylosing spondylitis." (PMID 32781731, 2020). "The intricate interplay between HLA-B27 and ERAP1 plays a critical role in the development of ankylosing spondylitis, and their distinct enzymatic activities significantly influence the peptide presentation process and the subsequent immune responses involving immunoglobulin receptors." (PMID 38534723, 2024). "ERAP1/2 polymorphisms, such as the ERAP1 Lys/Arg528 polymorphism, can affect MHC-I immunopeptidomes, the diversity of the response against infections and the onset of autoimmune responses such as Ankylosing Spondylitis." (PMID 34940832, 2021). "ERAP1 had genetic heterogeneity in a Swedish cohort with early onset ankylosing spondylitis." (PMID 34395615, 2021). "Aberrant peptide trimming by ERAP1 and a further impaired peptide presentation by HLA-B27 may be involved in the pathogenesis of ankylosing spondylitis." (PMID 33250919, 2020). "Further evidence in this direction comes from genome wide association studies (GWAS) pointing out that both Endoplasmic Reticulum aminopeptidase 1 (ERAP1), which is in an epistatic relationship with the HLA-B27, and ERAP2, are risk factors for Ankylosing Spondylitis (AS)." (PMID 31212633, 2019). "Together, our data suggests that ERAP1−/− mice may serve as a useful animal model for studying pathogenesis of intestinal, skeletal, and immunological manifestations of Ankylosing Spondylitis." (PMID 30127455, 2018). "This lack of regulation of the innate immune system by fully functional ERAP1 proteins may result in enhancing the likelihood of downstream precipitation of autoimmune diseases such as ankylosing spondylitis." (PMID 23894499, 2013). "For example, the presence of specific ERAP1 SNPs have correlated with the presence of several pathological conditions such as the chronic inflammatory disorder ankylosing spondylitis (AS), type I diabetes (T1D), multiple sclerosis (MS), Crohn’s disease (CD), Behcet's disease and hypertension." (PMID 23894499, 2013). "Polymorphisms linked to ERAP1 and ERAP2 genes are also associated with other HLA class I associated conditions that manifest with non-infectious uveitis, including HLA-B27-associated anterior uveitis and ankylosing spondylitis, or HLA-B51-associated Behcet’s disease." (PMID 33262772, 2020). "Indeed, plasma levels of ERAP1 and ERAP2 have been recently reported as markers of disease severity in inflammatory bowel diseases, preeclampsia, ankylosing spondylitis, and hepatitis B infection." (PMID 40226591, 2025). "Although the clinical connection between MSU crystals, the inflammasome, and ankylosing spondylitis are not well established, this data further supports ERAP1’s important role in general inflammasome and innate immune regulation." (PMID 35246034, 2022).
autoimmune disease (38 papers, 2011 to 2026). A disorder resulting from loss of function or tissue destruction of an organ or multiple organs, arising from humoral or cellular immune responses of the individual to their own tissue constituents. "For instance, in autoimmune diseases, ERAP1 variants rs30187 (K528R), rs27044 (Q730E), and rs17482078 (R725Q) have been associated with AS and Behçet’s disease." (PMID 40226591, 2025). "Genetic polymorphisms in ERAP1, leading to altered enzymatic activity, have been implicated in the pathogenesis of several autoimmune diseases, including IBD." (PMID 40977735, 2025). "ERAP1 haplotypes were previously studied in the context of several HLA class I-associated autoimmune diseases including Birdshot Chorioretinopathy (BSCR) and AS24–26." (PMID 37949852, 2023). "Genome-wide association studies (GWAS) have identified different single nucleotide polymorphisms (SNPs) in ERAP1 that are associated with several autoimmune diseases, including axSpA." (PMID 38024089, 2023). "Here we also suggest the important connection between ERAP1 and ER stress, uncovering new potential targets for the treatment, and/or prevention of ERAP1 linked autoimmune diseases." (PMID 35246034, 2022). "Our previous studies illustrated that ERAP1 polymorphisms in human cells enhance innate signaling, and recognize this as a possible cause for enhanced susceptibility to ERAP1 linked autoimmune diseases." (PMID 35246034, 2022). "ERAP1 gene polymorphisms causing improper ERAP1 functions have been linked to several autoimmune diseases; however, the exact molecular mechanisms underlying these associations are yet to be defined." (PMID 35246034, 2022). "Polymorphisms within ERAP1 correlate with predisposition to autoimmune diseases, pre-eclampsia, and cancer." (PMID 34489420, 2021). "Owing to its importance in the processing of antigens and regulation of the adaptive immune response, dysregulation of the highly polymorphic ERAP1 has been implicated in autoimmune disease and cancer." (PMID 33887439, 2021). "The ERAP1 single-nucleotide polymorphism (SNP) rs30187, which encodes lysine or arginine at position 528, has been associated with autoimmune diseases in epistasis with specific MHC alleles and alters the set of peptides presented by MHC6,7." (PMID 34489420, 2021). "Functional single nucleotide polymorphisms in ERAP1 have been associated with predisposition to several human diseases, including autoimmune diseases, viral infections and virally-induced cancer." (PMID 31341163, 2019). "ERAP1*001 contains five SNPs frequently reported with autoimmune disease association (ERAP1 M349V, K528R, D575N, R725Q and Q730E) and further confirms that ERAP1 SNPs occur in multiple combinations as previously reported." (PMID 30054427, 2018). "Currently, the presumed association of ERAP1 and autoimmune diseases has been suggested to be primarily mediated by its known role in MHC class I antigen presentation pathways, and potential downstream effects on T- and B-cell adaptive immune responses." (PMID 23894499, 2013). "Several genome-wide association studies (GWAS) have documented a critical role for ERAP1, with single nucleotide polymorphisms (SNPs) in ERAP1 being associated with predisposing individuals to autoimmune diseases." (PMID 23894499, 2013). "In autoimmune diseases, association with HLA-class I risk alleles and their interaction with ERAP1 implicates aberrant ER peptide trimming leading to altered peptide presentation as the pathogenic mechanism." (PMID 22942706, 2012). "In various autoimmune diseases ERAP1 variants show interactions with MHC class I risk alleles." (PMID 39570751, 2024). "ERAP1 is probably the most relevant example here because this aminopeptidase plays a major role in antigen processing through N-terminal peptide trimming into the ER and is associated with a number of different autoimmune diseases." (PMID 35141507, 2022).